DEFA6 (defensin alpha 6)
Description:
Host-defense peptide that contributes to intestinal innate immunity and mediates homeostasis at mucosal surfaces by forming higher-order oligomers that capture bacteria and prevent microbial invasion of the epithelium. After binding to bacterial surface proteins, undergoes ordered self-assembly to form fibril-like nanonets that surround and entangle bacteria and thereby prevent bacterial invasion across the epithelial barrier. Entangles and agglutinates Gram-negative bacteria, such as E.coli, S.typhimurium and Y.enterocolitica, and Gram-positive bacteria such as L.monocytogenes, thereby protecting the intestine against invasion by enteric bacterial pathogens. Blocks adhesion of C.albicans to intestinal epithelial cells and thereby suppresses fungal invasion of epithelial cells and biofilm formation. Under reducing conditions and in an acidic environment similar to the intestinal milieu, exhibits inhibitory activity against anaerobic bacteria such as B.adolescentis, L.acidophilus and B.breve, as well as B.longum and S.thermophilus, possibly by leading to alterations in bacterial cell envelope structures. The disulfide-linked oxidized form exhibits negligible antimicrobial activity against Gram-negative and Gram-positive bacteria, as compared to the enteric defensin DEFA5.
Synonyms: DEF6; HD-6
Tractability: Antibody: UniProt places it where antibodies can reach, with high confidence; its Gene Ontology location is reachable by antibodies, with high confidence; UniProt predicts a signal peptide or a membrane-spanning region.
Gene: Protein-coding gene on chromosome 8 (6,924,697 to 6,926,076, reverse strand). Ensembl gene ENSG00000164822.
Subcellular location: Secreted; Cytoplasmic vesicle, secretory vesicle
Pathways (Reactome):
Immune System: Alpha-defensins; Defensins
Gene Ontology:
Molecular function: protein binding; protein homodimerization activity; pore-forming activity
Biological process: antibacterial humoral response; antimicrobial humoral immune response mediated by antimicrobial peptide; defense response to Gram-negative bacterium; defense response to Gram-positive bacterium; disruption of plasma membrane integrity in another organism; innate immune response; defense response
Cellular component: extracellular region; Golgi lumen; transport vesicle
Genetic constraint (gnomAD): Loss-of-function variants: 5 observed, 3.76 expected, observed/expected ratio (o/e) 1.33, 90% interval 0.65 to 1.91. That is too few expected variants to judge how well the gene tolerates losing a copy. Missense variants: 168 observed, 110.02 expected, observed/expected ratio (o/e) 1.53, 90% interval 1.35 to 1.74. Synonymous variants: 70 observed, 43.88 expected, observed/expected ratio (o/e) 1.6, 90% interval 1.31 to 1.9.
Homologues: Orthologues: chimpanzee DEFA6 (99% identical), macaque DEFA6 (81% identical), rabbit MCP-1 (40% identical), rat Defa5 (39% identical), rat Defa31 (38% identical), rat Np4 (36% identical), rat RatNP-3b (35% identical), mouse Defa17 (34% identical), mouse Defa2 (34% identical), mouse Defa20 (34% identical), mouse Defa23 (34% identical), mouse Defa28 (34% identical), and 30 more. Paralogues in human: DEFA4 (47% identical), DEFA1 (46% identical), DEFA1B (46% identical), DEFA3 (46% identical), DEFA5 (46% identical).
Diseases named in the same sentence as DEFA6 in open-access papers:
DEFA6 is named in the same sentence as 23 diseases in open-access papers, as found by Europe PMC text mining. Sharing a sentence is not in itself a finding about the gene and the disease. The quoted sentences say what the papers report.
adenoma (6 papers, 2014 to 2025). A neoplasm arising from the epithelium. "To test this, we examined small intestinal adenomas in Apc+/Min mice crossed with Rosa26-tdTomato/Defa6-iCre mice and detected scattered Defa6-tdTom+ cells within the adenomas." (PMID 40221753, 2025). "In C2 goblet cells, during the process from normal colon to adenoma and from adenoma to carcinoma, several continuously highly expressed genes were found, including DEFA6, SOX9, ID1, L1TD1, CXCL3, and ODC1." (PMID 36944972, 2023). "And the 6 coincident genes significantly enriched in adenoma and carcinoma were DEFA6, SOX9, ID1, L1TD1, CXCL3, and ODC1." (PMID 36944972, 2023). "Immunohistochemistry (IHC) experiments showed that the expression of DEFA6 was significantly higher in adenoma than in normal mucosa and slightly higher in carcinoma than in normal mucosa." (PMID 36703795, 2022). "In cancer-adenoma, we also found downregulation of DEFA5 and DEFA6, which encode α-defensins and are primarily expressed in Paneth cells of the small intestine." (PMID 31211760, 2019). "The intensity of DEFA6 staining in adenoma was obviously deeper than that in normal tissues." (PMID 36703795, 2022). "Similar to small adenomas in the small intestine of Apc+/Min mice, adenomas examined three weeks after AOM/DSS treatment contained only scattered Defa6-tdTom+ cells." (PMID 40221753, 2025).
colon carcinoma (6 papers, 2010 to 2025). "We next sorted and analyzed Defa6-tdTom tumor cells from the colon tumors of Apc+/Min/ROSA26-tdTomato/Defa6-iCre and Tcf7l2flox/flox/Apc+/Min/ROSA26-tdTomato/Defa6-iCre mice using bulk RNA-seq." (PMID 40221753, 2025). "The expression of DEFA6 in colon cancer, rectal adenocarcinoma, thymic cancer, and gastric cancer was significantly higher than that in normal tissues." (PMID 36703795, 2022). "Expression microarray data analysis obtained from 283 tumors and normal tissues showed that DEFA6 was maximally expressed in colon cancer." (PMID 36703795, 2022). "Compared to adjacent normal colon, upregulation of Defa6 and Bcl3 and downregulation of App, Myh11, and Myl9 indicated changes in tight junctions and anti-microbial activity in Pirc colon tumors." (PMID 34494932, 2021). "DEFA6 were found to promote the occurrence of colon adenoma and colon cancer." (PMID 36703795, 2022).
colorectal cancer (4 papers, 2010 to 2024). A primary or metastatic malignant neoplasm that affects the colon or rectum. "Moreover, DEFA5 may be associated with better prognosis of colorectal cancer, while DEFA6 may be linked to a worse prognosis." (PMID 36982340, 2023). "In contrast to this, DEFA5 and DEFA6 expression is significantly increased in colorectal cancer compared to healthy tissues." (PMID 36982340, 2023). "More data is needed, but DEFA5 and DEFA6 seem to have a promising degree of specificity and sensitivity for predicting the prognosis of colorectal cancer." (PMID 36982340, 2023). "The median gene expression of human defensin alpha 6 (DEFA 6) has been found to be moderately increased (~ 5 fold) in tumor samples derived from individuals with colorectal cancer (CRC) when compared to their normal counterparts." (PMID 20979654, 2010). "Further, we searched for 100 related genes of DEFA5 and DEFA6 in colorectal cancer, and speculated the possible role of them in the carcinogenesis of colorectal cancer by analyzing the role and pathway of the top genes." (PMID 36703795, 2022).
colitis (2 papers, 2011 to 2018). Inflammation of the colon. "EtOH feeding caused dramatic reduction of colitis-induced expression of Defa4, Defa5 and Defa6 genes." (PMID 30389960, 2018). "Interestingly, HD5 feeding caused a partial prevention of EtOH effect on colitis-induced expression of Defa4, Defa5 and Defa6 genes in colon." (PMID 30389960, 2018). "HD5 feeding partially blocked the effect of EtOH and DSS-colitis on Defa5 and Defa6 mRNA, but the effect on the mRNA for Defa4 gene was further reduced." (PMID 30389960, 2018). "The expression of Defa4, Defa5 and Defa6 genes was induced by colitis in the colon and EtOH feeding abolished this effect of colitis." (PMID 30389960, 2018). "Results of our present study show that DSS-induced colitis induces Defa4, Defa5 and Defa6 expression in mouse colon, and that EtOH feeding abrogates the colitis-induced expression of defensins in colon." (PMID 30389960, 2018). "DSS-induced colitis also elevated expression of Defa4 and Defa6 genes in the ileum." (PMID 30389960, 2018). "Confocal immunofluorescence microscopy showed the predominant localization of DEFA6 in the crypt epithelial cells in the colon of DSS-treated mice, but it was very low in the colon of EtOH-fed DSS-colitis mice." (PMID 30389960, 2018). "Tissue samples from IBD and pseudomembranous colitis were examined with routine histology and immunohistochemical analysis for REGIα, REGIV, DEFA6, and serotonin." (PMID 21992413, 2011). "DSS-induced colitis significantly elevated mRNA for Defa4 and Defa5, but not Defa6 genes in the ileum." (PMID 30389960, 2018).
colon adenoma (2 papers, 2022 to 2025). An adenoma that arises from the colon. "After FACS isolation and Matrigel culture of colon adenoma cells, we confirmed the ability of Defa6-tdTom cells to form organoids." (PMID 40221753, 2025). "In contrast, the more advanced colon adenomas of Apc+/Min mice showed clusters or glands of Defa6-tdTom cells in addition to scattered cells." (PMID 40221753, 2025). "Other studies also found significantly increased DEFA6 expression in colon adenoma and cancer." (PMID 36703795, 2022). "DEFA5 and DEFA6 are considered as key factors in colon adenoma formation." (PMID 36703795, 2022). "However, we observed the presence of Defa6-tdTom+ cells in mice when DSS administration was preceded by treatment with the mutagen azoxymethane (AOM), as well as in colon adenomas in Apc+/Min mice." (PMID 40221753, 2025).
gastric cancer (2 papers, 2012 to 2022). A primary or metastatic malignant neoplasm involving the stomach. "In conclusion, our findings suggest DEFA6, DEFB1, and INSL3 genetic variants are susceptibility factors for the development of gastric cancer." (PMID 23028900, 2012). "Thus, it is possible that some variants in DEFA6 and DEFB1 affect the susceptibility to gastric cancer by modifying the inflammatory response through changes in the expression or function of those proteins." (PMID 23028900, 2012). "Our findings suggest that DEFA6 rs2738120 (located in the intron) and DEFB1 rs2702829 (located in the 3′ of STP) have potential genetic effects on the development of gastric cancer." (PMID 23028900, 2012). "In the Replication genotyping phase with more case-control sets and in the meta- and pooled analyses, DEFA6, DEFB1, and INSL3 were still significantly associated with gastric cancer risk without heterogeneity across the phases." (PMID 23028900, 2012). "Four SNPs had no heterogeneity across the phases: in the meta-analysis, DEFA6 rs13275170 and DEFB1 rs2738169 had both a 1.3-fold increased odds ratio (OR) for gastric cancer (95% CIs = 1.1–1.6; and 1.1–1.5, respectively)." (PMID 23028900, 2012).
Autoimmunity (1 paper, 2026). The occurrence of an immune reaction against the organism's own cells or tissues. "Also, Paneth cells (PCs) as the only cells of the immune periphery with an active Defa6 promoter (the driver of OVA in OVA+Cldn1+/+ and OVA+Cldn1−/− chimeras) showed similar numbers in the ileum of all BM chimeras, further supporting the negligible role of OTIIs in the observed autoimmunity." (PMID 41481333, 2026).
colorectal adenocarcinoma (1 paper, 2022). The most common type of colorectal carcinoma. "In the Oncomine and TCGA databases, we found the significantly higher expression of DEFA6 in CRC than that in normal tissues, especially in colorectal adenocarcinoma." (PMID 36703795, 2022).
colorectal tumors (1 paper, 2025). "The Defa6-iCre driver was also used for cell labeling and cellular composition analysis of colorectal tumors." (PMID 40221753, 2025). "We used this finding to test whether the Defa6-iCre driver can specifically mark nascent colorectal tumor cells." (PMID 40221753, 2025).
enteritis (1 paper, 2025). Inflammation of the small intestine. "The experimental data revealed good discrimination for DUOX2, LCN2, and DEFA6 in normal individuals, enteritis patients, and IBD patients." (PMID 40830794, 2025).
pancreatic cancer (1 paper, 2022). "Based on cBioPortal, we analyzed the mutation rate of DEFAs in CRC, the mutation rates of DEFA6 in pancreatic cancer, and the correlations between the mRNA expression of DEFAs in patients with CRC (Pearson correlation coefficient)." (PMID 36703795, 2022). "In pancreatic cancer, the mutation rates of DEFA6 were analyzed using the TCGA database." (PMID 36703795, 2022).
ulcerative colitis (1 paper, 2012). An inflammatory bowel disease involving the mucosal surface of the large intestine and rectum. "The selected transcripts included the alpha defensins, (DEFA5 and DEFA6), which have exhibited altered regulation in ileal Crohn’s disease, and included cellular detoxification genes, which have exhibited altered regulation in ulcerative colitis." (PMID 22719822, 2012).
tumor (8 papers, 2010 to 2025). "Using conditional alleles of Tcf7l2 and Apc in combination with Defa6-iCre, we were able to analyze the effects of Tcf4 loss on a subpopulation of cells within the developing tumor." (PMID 40221753, 2025). "Next, we investigated the effects of Tcf4 deficiency in tumor cells expressing Defa6-iCre." (PMID 40221753, 2025). "DEFA6 promotes tumor progression and is associated with poor prognosis." (PMID 36703795, 2022). "An exception was cluster 3 (secretory progenitor cells), which according to immunohistochemical staining for Muc2 consists of Defa6-tdTom cells distributed throughout the tumor." (PMID 40221753, 2025). "Another protein significantly more abundant in MMPhigh was DEFA6, a protein expressed in normal Paneth and Paneth-like tumor cells." (PMID 33806447, 2021). "Interestingly, the cells positive for Tacstd2 formed clusters in the tumor including glandular structures labeled with Defa6-iCre; however, the scattered Defa6-tdTom cells were predominantly Tacstd2-negative." (PMID 40221753, 2025). "High proliferative goblet cells expressing MKI67 and metaplastic paneth cells expressing antimicrobial α‐defensins (DEFA5 and DEFA6) were enriched in precancerous and tumor tissues comparing with adjacent tissues, suggesting they might play a role in tumorigenesis." (PMID 34185431, 2021). "Moreover, the differential roles of specific defensins (e.g., tumor-suppressive DEFA5 vs. tumor-promoting DEFA6) highlight the complexity of AMP regulation in CRC and suggest that targeted modulation of AMP pathways could represent a novel therapeutic strategy for CRC." (PMID 40585846, 2025). "Among the co-expressed genes shared by DEFA5 and DEFA6, KLK12, which is responsible for tumor formation, was highly expressed in CRC." (PMID 36703795, 2022). "Remarkably, the organoid-forming efficiency of Defa6-tdTom cells was significantly reduced compared to non-tdTomato-labeled tumor cells, with the former forming smaller and slower proliferating organoids after the first passage." (PMID 40221753, 2025). "These Paneth-like cells, identified by markers such as DEFA6 and LYZ, are essential for propagating tumor organoids and are found in tumor regions where cell adhesion is lost, suggesting they play a key role in maintaining the CSC niche and supporting tumor growth." (PMID 41002393, 2025).
cancer (6 papers, 2019 to 2023). A tumor composed of atypical neoplastic, often pleomorphic cells that invade other tissues. "DEFA6 staining in carcinoma was slightly deeper than that in normal tissues." (PMID 36703795, 2022). "There are 10 highly significant, direct and physical associators with a confidence score of ≥5.0 namely – RELA, HMOX2, EZH2, p-10Y-ERBB3-1, WDR1, ERRFI1, PRG2, FMR1, DEFA6-(?-100), cytf_human and the majority of the network associators of POTEE are epigenetically activated in many cancers." (PMID 34788504, 2021).
infection (5 papers, 2020 to 2025). The state of being infected such as from the introduction of a foreign agent such as serum, vaccine, antigenic substance or organism. "To validate the key role of IL-18-Stat3 signalling in Paneth cells during AIEC infection, we investigated how the injection of recombinant IL-18 into Defa6-Cre+Stat3f/f mice contributes to AIEC host defence." (PMID 35169117, 2022). "Paneth cell number was modestly reduced in the small intestine of Il22Ra1fl/fl;Defa6-cre+ mice after infection." (PMID 33060802, 2021). "Ileal RNA expression of the alpha-defensin AMPs, Defa5, and Defa6, as well as MMP7, was significantly lower in Ptpn2∆IEC vs. Ptpn2fl/fl mice, after mAIECred but not K12 infection." (PMID 40955058, 2025).
intestinal diseases (1 paper, 2025). "Inhibiting the FOXO signaling pathway can effectively restore the expression of DEFA6, which is highly important for the study of intestinal diseases and the enhancement of intestinal immunity." (PMID 40830794, 2025).
DEFA6 also shares sentences with these, for which no sentence is quoted: necrotizing enterocolitis (2 papers); bladder urothelial carcinoma (1); hepatocellular carcinoma (1); lung squamous cell carcinoma (1); Obesity (1); ovarian serous cystadenocarcinoma (1); rectal adenocarcinoma (1).